WRN (WRN RecQ like helicase)
Diseases named in the same sentence as WRN in open-access papers (continued):
Sharing a sentence is not in itself a finding about the gene and the disease.
tumor (65 papers, 2010 to 2026). "Highlighting the importance of WRN in DNA repair, WRN has been identified as a synthetic lethal target in microsatellite instability-high (MSI-H) tumor types that are deficient in mismatch repair (MMR) pathways." (PMID 39025847, 2024). "The tumor suppressor WRN encodes an enzyme from the RECQ gene family, which is essential for maintaining genomic stability." (PMID 37628631, 2023). "Our analyses of tissue, tissue sections and tumor DNA from four well-characterized, WRN mutation-confirmed WS patients coming to autopsy provide new information on WS cellular, molecular and genomic features." (PMID 27559010, 2016). "In both cases tumor growth was significantly delayed, and as predicted, WRN loss of function in the context of robust Myc activation led to the elevation of a DNA damage response resulting in cellular senescence and tumor necrosis." (PMID 22373487, 2012). "These contradictory observations that WRN loss in WS patients leads to increased and accelerated tumorigenesis while cells with WRN deficiency inhibit tumor cell growth suggests a complex role for WRN in tumorigenesis." (PMID 21267443, 2011). "Interestingly, the tumor suppressor p14ARF stimulated WRN SUMOylation, and this modification was linked to the exclusion of WRN from the nucleolus." (PMID 39125869, 2024). "Furthermore, the aberrant function of the WRN gene in MSI-H CRC tumors, as a result of frameshift variants, suggested the probability of WRN contribution at MSI-H tumorigenesis as a putative tumor suppressor." (PMID 34164337, 2021). "Hence, the restoration of WRN expression induces tumor-suppressor-like features and inhibits tumor growth and associated carcinogenesis." (PMID 33477997, 2021). "Mice with homozygous deficiency for WRN were viable and developed tumours by 2 years of age." (PMID 23036272, 2012). "RECQL4 is a member of a family of DNA helicases including Bloom (BLM) and Werner (WRN) helicases, All three members are associated with familial cancer predisposition syndromes with high frequencies of mesenchymal derived tumours, with RTS in particular developing OS at approximately 30% frequency." (PMID 23036272, 2012). "However, it should be noted that WRN has a tumor suppressor function, and the loss of its second wild-type allele is necessary for carcinogenesis events to fulfill Knudson’s two-hit hypothesis of tumor suppressor genes." (PMID 34164337, 2021). "Moreover, it would be important to define the frequency of WRN mutations in other tumor entities." (PMID 32455893, 2020). "More importantly, this hypothesis can be applied to WRN deficiency in general, in which the combination of WRN deficiency and the functional loss of other critical genes could accelerate this transformation and subsequently promote tumor formation." (PMID 21267443, 2011). "Combination with irinotecan further enhanced tumor regressions, consistent with synergy between induced replication stress and WRN blockade." (PMID 41190241, 2025). "Preclinical data show selective lethality in MSI-H cells, proteasomal degradation of bound WRN, and robust tumor regressions in multiple MSI-H xenograft and PDX models, with minimal effects in MSS controls." (PMID 41190241, 2025). "Given the uncertainty of how effective inhibitors of WRN activity will prove in clinical trials, and the likelihood of tumours developing resistance to WRN inhibitors, alternative strategies for impeding WRN function are needed." (PMID 39242638, 2024). "This discovery has prompted efforts to target WRN pharmacologically as a novel precision strategy against MSI tumours, alone or in combination with other therapies." (PMID 38587317, 2024).
tumor (continued). "Given that in vitro treatment of WRNi in HCT-116 cells led to WRN degradation, we decided to measure WRN protein levels from tumor samples." (PMID 39025847, 2024). "To assess the potency and selectivity of the WRN inhibitors, we evaluated their effect on in vitro viability in curated collections of cell lines and patient-derived tumour organoids." (PMID 38587317, 2024). "Taken together, these data show that conditional PROTAC-mediated WRN degradation is a valid approach for treating MSI tumours." (PMID 39242638, 2024). "In summary, these results demonstrate that our WRN inhibitors phenocopy the effects of genetic WRN inactivation in MSI tumours." (PMID 38587317, 2024). "In summary, our functional experiments demonstrated that inhibiting LIMK1 reduces cellular senescence and inhibits tumor cell proliferation, while reducing WRN has the opposite effect, indicating their potential as therapeutic targets." (PMID 37828981, 2023). "Here, we discuss possible paths of MSI tumour development, the viability of WRN inhibition as a strategy in different scenarios, and the necessary conditions to create a roadmap towards successful implementation of WRN inhibitors in the clinic." (PMID 36379964, 2022). "In sum, the roadmap towards clinical applications of WRN inhibitors is paved by roadblocks in drug development, tumour profiling, and patient stratification." (PMID 36379964, 2022). "Collectively, mounting evidence supports the potential of future WRN inhibitors to selectively treat a subset of MSI tumours." (PMID 36379964, 2022). "Recent work has unveiled a promising synthetic lethal interaction between inactivation/inhibition of the WRN DNA helicase and tumours with microsatellite instability, a phenotype that arises from DNA mismatch repair deficiency." (PMID 36379964, 2022). "In tumor cell lines, the co-occurrence of WRN inactivation and MSI leads to cell death and cell cycle arrest via the acquisition of double-strand breaks and chromosomal instability." (PMID 32455893, 2020). "WRN-mut CRCs were associated with a higher mean tumor mutational burden (TMB) (49 vs. 10.7 mutations/megabase [mut/MB], p < 0.0001) and a higher PD-L1 expression (13% vs. 4%, p < 0.0001) compared to WRN-wt." (PMID 32455893, 2020). "As WRN participates in various DNA repair pathways, it is possible that it enhances the DNA repair capabilities of established tumor cells to withstand DNA damage induced by endogenous and exogenous agents." (PMID 26959889, 2016). "A Student’s t-test for CN differences between the sensitive and resistant tumor cells of temsirolimus’ minimal EN model finds the most significant difference (p<0.00044) for the DNA helicase protein, WRN." (PMID 26132924, 2015). "We also found that expression of the triplex/G-quadruplex-unwinding helicase WRN correlated significantly with total triplex DNA-binding activity in EMSAs in both normal and tumor tissue extracts." (PMID 22682314, 2012).
tumor (continued). "We used the Wilcoxon sign rank test to determine if WRN is differentially expressed in normal and tumor tissue extracts and Spearman’s rho to correlate WRN helicase expression in normal and tumor tissue extracts with EMSA H3 data." (PMID 22682314, 2012). "Increasing evidence supports that Werner protein (WRN), a RecQ helicase and exonuclease, plays a direct role in telomere maintenance and promotion of tumor cell growth." (PMID 22545052, 2012). "In addition, MOMA‐341 is a new, potent and selective small‐molecule WRN inhibitor in clinical‐stage development that induces DNA damage, cell death and tumour regression in dMMR/MSI‐H models." (PMID 41537447, 2026). "GSK4418959 is an oral allosteric WRN inhibitor that exerts SL in dMMR/MSI‐H tumours." (PMID 41537447, 2026). "WRN has recently been identified as a novel SL target in MSI tumours." (PMID 41537447, 2026). "WRN is a promising synthetic lethal target for MSI tumours, and WRN inhibitors are in development." (PMID 38587317, 2024). "Notably, tumours expressing the helicase point mutant WRN(K577A) upregulated its expression to compensate for the loss of endogenous WRN as an escape mechanism and revealed that the K577A helicase mutant retains a very low level of activity." (PMID 38658754, 2024). "WRN inhibitors have shown potent anti-tumor effect in in vitro and in vivo MSI-H tumor models." (PMID 39655075, 2024). "Thus, developing potent and selective WRN helicase inhibitors and their detailed pre-clinical evaluation remains an important next step to validate the synthetic-lethal effect of WRN in MSI tumours following pharmacological inhibition." (PMID 38587317, 2024). "Furthermore, it appears that the mechanism of action is recapitulated in mice, as evidenced by WRN degradation in tumor samples after treatment with WRNi." (PMID 39025847, 2024). "Therefore, further coupling of the nucleotide enzyme WRN on TM helped in clearing ecDNA, enhancing the efficacy of inducing tumor fibrosis." (PMID 39206698, 2024). "Combining with high selectivity of WRN helicase inhibitors in MSI-H tumor cells over MSS normal cells, we are expecting a low safety risk in clinic and we are waiting for clinical data to verify the hypothesis." (PMID 39655075, 2024). "This insinuates that LIMK1 knockdown could curtail tumor cell proliferation, while WRN knockdown could stimulate it." (PMID 37828981, 2023). "Moreover, WRN depletion reduced xenograft growth and tumour formation in mice transplanted with MSI cells." (PMID 36379964, 2022). "Since WRN inhibition would be effective only on the MSI cells that have developed (TA)n repeat expansions, a considerable proportion of the cells in such a tumour could be unaffected, likely causing failure to respond or relapse." (PMID 36379964, 2022). "Tumor cell growth was significantly inhibited by RECQL1-or WRN-silencing by siRNA." (PMID 35782872, 2022). "Moreover, the HRD phenotype was observed in this relapse lesion, probably due to a somatic LOH of WRN acquired during tumor progression." (PMID 33920370, 2021). "The WRN gene was recognized as a tumor-suppressor gene and evidence suggests that it plays a role in promoting oncogenic proliferation which may likely contribute to AML transformation in Patient 5, in addition to the NPM1 and IDH2 mutations." (PMID 34560908, 2021). "The results of this study uncover a novel vulnerability of MSI-H tumor cell models and indicate that pharmacological inhibition of WRN ATPase/helicase function might serve as an attractive targeted therapeutic strategy in MSI-H cancer." (PMID 30910006, 2019). "In addition, the requirement for WRN in ALT is associated with an ALT-specific interaction between WRN and the BRCA1 tumor suppressor." (PMID 24709898, 2014).
tumor (continued). "Interestingly, many cancer cell lines express relatively high levels of WRN, which is necessary for growth, anchorage-independent growth, and tumor formation in animal models." (PMID 24757718, 2014). "The differential resistance to oxidative stress between normal and cancer cells in response to acute WRN knockdown suggests that drugs targeting WRN could be used to hypersensitize tumor cells." (PMID 24757718, 2014). "Nevertheless, somatic mutations of WRN gene have not been found in sporadic malignancies, but epigenetic-mediated silencing was reported in many tumor types of epithelial and mesenchymal lineage in a parallel way observed in MLH1." (PMID 22778947, 2012). "These ALT tumors appeared to be type II, but the possibility of ALT type I tumor formation by WRN-deficient cells cannot be ruled out." (PMID 22545052, 2012). "Therefore, our current investigation also provides insights to establish a foundation to devise new synthetic lethal strategies by combining CHK1 or PARP1 inhibitors with TOP1 inhibitors to counteract WRN and NF‐κB mediated intrinsic tumor resistance in clinical settings." (PMID 35582959, 2022). "Given its high expression in certain tumor tissues and its inhibition of several tumor suppressor genes like FOXO1, p73, and WRN, SIRT1 is believed to promote tumorigenesis." (PMID 39944690, 2025). "continuously treated MSI-H tumor cells (HCT116 and SW48) with HRO761 and other WRN inhibitors showing a similar mechanism of action." (PMID 39655075, 2024). "Together, these in vivo studies demonstrate that GSK_WRN4 exerts potent anti-tumor activity in MSI models while sparing MSS controls, inducing hallmarks of WRN-inhibition-mediated DNA damage." (PMID 38587317, 2024). "WRN inhibition leads to replication fork collapse, DNA double-strand breaks, and subsequent apoptosis in MSI-H tumor cells." (PMID 39655075, 2024). "FEN1 protects perturbed forks from erroneous over-resection by MRE11 through regulating of BRCA1-RAD51 and WRN helicase, uncovering an essential genetic interaction between FEN1 and DNA-PKcs in mitigating replication-stress induced tumor genomic instability." (PMID 35414100, 2022). "As described recently, the helicase domain of WRN is considered as a therapeutic target for synthetic lethality, as the exonuclease domain is dispensable for cell survival in MSI-H tumor cells." (PMID 32455893, 2020). "In this review, we pay special attention to recent studies on RECQL1-siRNA and WRN-siRNA that down-regulate the expression of RECQL1 and WRN helicases, respectively, and exert a tumor-specific killing effect on a wide range of tumor cells." (PMID 25620975, 2014). "Among tumor suppressor genes altered by copy-number losses, RB1 and WRN were also present in regions of recurrent copy-neutral LOH." (PMID 21151896, 2010). "A strong, particular WRN inhibitor is HRO761.The phenotypes shown with WRN gene inhibition were recapitulated by pharmacological inhibition of HRO761, which resulted in tumor development and DNA damage in MSI cells while selectively inhibiting cell proliferation." (PMID 40240755, 2025). "Indeed, WRN degradation was observed in the tumors from all dose groups, suggesting that WRNi achieved in vivo target engagement in an HCT-116 xenograft tumor model in mice." (PMID 39025847, 2024). "GSK_WRN4 induced DNA damage specifically in MSI-H tumors, but not other tissues, demonstrating that the in vivo tumor growth inhibition by GSK_WRN4 at 300 mpk is due to WRN helicase inhibition rather than off-target toxicity." (PMID 38587317, 2024). "We identified 42 and 16 TSGs monoallelically deleted in P2 and P5, respectively, including several TSGs deleted in both tumor samples (ARHGEF10, CDKN1B, ETNK1, ETV6, LEPROTL1, NRG1, PTPN6, and WRN) and many TSGs co-deleted in the same subclone as well as across multiple subclones." (PMID 38658552, 2024).
tumor (continued). "Therefore, the prognostic significance of LIHC was significantly influenced by factors such as pathological stage, tumor status, and the expression levels of RECQL, WRN, RECQL4, and RECQL5." (PMID 37626815, 2023). "Previous studies on the WRN gene are based on the mechanism of physiological or tumor pathophysiological progression, whereas there are no studies or reports on the mutation of drug resistance." (PMID 33225619, 2021). "Various degradative enzymes, either in the tumor cells or in host cells, are induced to do so by tumor-derived factors related to retinoid signaling such as RAI2 or through retinoid-independent metastasis modulators such as WRN, IGF1-R, TGF-β1 and E-cadherin." (PMID 33477997, 2021). "Our data suggest that similar to the tumor agnostic activity of checkpoint blockade, MMR deficiency and MSI-H status represent a genetic determinant for WRN dependency regardless of tumor type." (PMID 30910006, 2019). "Analysis of many human primary tumors showed that hypermethylation of the WRN promotor is a common event in various tumor cells and is indicative of tumorigenesis by the absence of WRN expression." (PMID 25620975, 2014). "Similarly, local injections of WRN-siRNA and RECQL1-siRNA formulated with atelocollagen into a mouse zenograft model of hypopharyngeal carcinoma markedly inhibits tumor growth." (PMID 25620975, 2014). "This also suggests that WRN plays an important role in the recombination-based mechanism (similar to yeast Type II survivors) used to maintain telomeres in the majority of ALT+ cell lines and tumours." (PMID 22989712, 2012). "However, we did observe that total WRN expression correlated significantly with total EMSA H3 binding values in both normal tissue (rho 0.296, p = 0.03) and tumor extracts (rho 0.460, p < 0.001)." (PMID 22682314, 2012). "Moreover, WRN depletion in MSI cells reduced xenograft growth and tumour formation in mice." (PMID 38658754, 2024). "In the absence of a functional WRN protein, accumulation of deletions and translocations could potentially inactivate tumor suppressor genes or activate oncogenes, accelerating tumor formation and/or aggressiveness." (PMID 27863399, 2016). "Together these results suggest that WRN, but not the other RecQs, is a target of CPT in mediating chemotherapeutic effects in the tumor cells." (PMID 26959889, 2016).
genetic disorders (18 papers, 2010 to 2024). "Mutations in WRN, BLM, or RECQL4 cause different genetic disorders, all associated with accelerated aging, genomic instability and tumorigenesis." (PMID 32820027, 2020). "Mutations in WRN and BLM are associated with the rare genetic diseases Werner and Bloom syndromes, respectively." (PMID 25400656, 2014). "WRN, BLM, and RTS are involved in genetic disorders associated with genomic instability and a high incidence of cancer." (PMID 25424877, 2014).
cardiovascular disease (3 papers, 2008 to 2025). "Studies carried out on polymorphic WRN locus have shown that the alleles 1367R and 1074L confer protection for cardiovascular disease." (PMID 18312663, 2008).
colorectal (1 paper, 2024). "Furthermore, AGB-1 treatment resulted in an equivalent or marginally greater elimination of the mCherry HCT-116 Bd-WRN cells when compared with HRO761, an allosteric WRN inhibitor with a growth inhibitory 50% (GI50) of 40 nM, currently in phase I clinical trials for MSI colorectal cancers." (PMID 39242638, 2024).
infection (1 paper, 2017). The state of being infected such as from the introduction of a foreign agent such as serum, vaccine, antigenic substance or organism. "Efficient replication of the HSV-1 genome is limited in the absence of host factors such as ATM, MRN, or WRN, indicating that such factors promote productive infection." (PMID 29144403, 2017).
metabolic disorders (1 paper, 2018). "Moreover, it is recognized that deficiency in DNA repair machinery such as ATM, WRN, and Ercc1, accelerates aging and causes severe metabolic disorders." (PMID 29717979, 2018).